FMNL2 (formin like 2)
Diseases named in the same sentence as FMNL2 in open-access papers (continued):
Sharing a sentence is not in itself a finding about the gene and the disease.
breast carcinoma (continued). "Compared to lower proliferative cells MCF7 and T47D, FMNL2 was overexpressed in highly proliferative breast cancer cells MDA-MB-231, BT549 and SUM159, accompanied by reduced levels of p27 and p21, and elevated CyclinD1 and Ki67 expression." (PMID 34193109, 2021). "Further, we investigated the effect of FMNL2 overexpression on cell proliferation of human breast cancer." (PMID 34193109, 2021). "We also speculated that p27 phosphorylation might be involved in the regulation of the cytoplasmic distribution of p27 in FMNL2-mediated breast cancer cell migration and invasion." (PMID 35379791, 2022). "Taken together, we may conclude that FMNL2 suppressed migration and invasion of breast cancer cells by inhibiting RhoA/LIMK/Cofilin pathway through a reduction of cytoplasmic p27." (PMID 35379791, 2022). "In all, these data suggest that the effects of FMNL2 on breast cancer metastasis may be contributed by the regulation of RhoA/LIMK/Cofilin pathway." (PMID 35379791, 2022). "We further found that ERα might be a negative regulator for FMNL2 at the posttranslational level in breast cancer, implying that FMNL2 expression partially depended on ER status." (PMID 35379791, 2022). "Furthermore, ERα overexpression reduced the protein levels of FMNL2 in breast cancer cells, which were reversed by MG132." (PMID 35379791, 2022). "However, our data indicated that FMNL2 interacted with RhoA, other than Rac1 in breast cancer cells." (PMID 35379791, 2022). "We found that FMNL2 reduced cell migration and invasion of breast cancer in vitro and in vivo." (PMID 35379791, 2022). "Considering cytoplasmic 27 has been reported to be implicated in invasion and metastasis of cancer progression, we speculated whether cytoplasmic 27 was involved in FMNL2-mediated cell migration and invasion of breast cancer." (PMID 35379791, 2022). "This requires more research to explore whether lysosomal degradation of p27 was involved in FMNL2-regulated cell proliferation of breast cancer." (PMID 34193109, 2021). "Therefore, our results demonstrated that FMNL2 overexpression elevated cell proliferation in human breast cancer MCF7 cells." (PMID 34193109, 2021). "Next, we explored whether FMNL2 played a functional role in cell proliferation of breast cancer in vitro." (PMID 34193109, 2021). "Furthermore, FMNL2 suppressed the nuclear levels of p27 and promoted p27 proteasomal degradation in human breast cancer cells." (PMID 34193109, 2021). "Moreover, there is also a significant positive correlation between FMNL2 and Ki67 in breast cancer samples from the TCGA database." (PMID 34193109, 2021). "Therefore, our findings demonstrated that FMNL2 silencing inhibited EdU incorporation and induced cell cycle arrest in human breast cancer cells." (PMID 34193109, 2021). "Unlike those studies reporting the positive role of FMNL2 in several cancers, our results illustrated that FMNL2 silencing promoted cell migration and invasion of breast cancer in vitro and in vivo, suggesting that FMNL2 may function as a negative regulator of breast cancer migration and invasion." (PMID 35379791, 2022). "Therefore, we further investigated whether cytoplasmic p27 was involved in FMNL2-mediated breast cancer cell migration and invasion." (PMID 35379791, 2022). "Besides, the expression of FMNL2 was negatively correlated with ER status in breast cancer tissues." (PMID 34193109, 2021). "Additionally, FMNL2 was negatively correlated with ER status in breast cancer tissues (P < 0.05)." (PMID 34193109, 2021). "Thus, we may conclude that FMNL2 silencing inhibited cell proliferation in human breast cancer cells." (PMID 34193109, 2021). "Indeed, the migration-promoting effects and the enhanced RhoA/LIMK/Cofilin pathway induced by FMNL2 silencing could be abrogated by ZOL or BMS3, highlighting the involvement of RhoA/LIMK/Cofilin pathway in FMNL2-mediated inhibition of breast cancer cell migration and invasion." (PMID 35379791, 2022).
breast carcinoma (continued). "Our data demonstrated that FMNL2 silencing promoted the phosphorylation of LIMK/Cofilin pathway, thus contributing to elevated F-actin polymerization and increased breast cancer cell migration and invasion." (PMID 35379791, 2022). "Further, FMNL2 disrupted actin cytoskeleton rearrangement and hampered the RhoA/LIMK/Cofilin pathway in breast cancer cells." (PMID 35379791, 2022). "We noticed that FMNL2 and FMNL3 were upregulated in metastatic breast cancer cell lines." (PMID 38296970, 2024). "In the current study, FMNL2 was downregulated in breast cancer cells when compared to non-cancerous MCF10A cells." (PMID 35379791, 2022). "Firstly, we found that FMNL2 protein was highly expressed in non-cancerous MCF10A cells when compared to breast cancer cells." (PMID 35379791, 2022). "Compared to lower proliferative cells MCF7 and T47D, highly proliferative breast cancer cells MDA-MB-231, BT549 and SUM159 expressed high levels of FMNL2 along with high proliferative features including enhanced Ki67 and CyclinD1 levels, and reduced levels of p27 and p21." (PMID 34193109, 2021). "In all, our data indicated that FMNL2 may promote CDK4/CyclinD1 kinase activity and cell proliferation through inhibition of p27 nuclear localization and p27 protein stability in human breast cancer cells." (PMID 34193109, 2021). "Obviously, the results of in vitro assays indicated that the positive role of FMNL2 in cell proliferation of human breast cancer cells was not correlated with ER status." (PMID 34193109, 2021). "With the exception of UQCRH and LRP8, the expression levels of genes positively correlated with YBX1, such as CTPS1, FMNL2, CDC20, B3GNT5, MTHFD1L, and CDCA8, were significantly and positively correlated with the expression level of YBX1 in 13 breast cancer cell lines." (PMID 30647855, 2018). "FMNL2 silencing did not affect the invasive capacity of breast carcinoma cells or fibrosarcoma cells, which display a more mesenchymal elongated morphology." (PMID 20633255, 2010). "In our previous study, FMNL2 is inconsistently expressed in the cytoplasm and nucleus of non-cancerous breast epithelial MCF10A cells and breast cancer cells, and further, nuclear p27 levels play a crucial role in FMNL2-mediated breast cancer cell proliferation." (PMID 35379791, 2022). "However, despite that, the effects of FMNL2 on breast cancer cell migration and invasion have not been reported yet." (PMID 35379791, 2022). "Interestingly, without nucleocytoplasmic transport of p27, FMNL2 also decreased cytoplasmic p27 levels in breast cancer cells." (PMID 35379791, 2022). "After incubation with ZOL or BMS3, FMNL2 expression was profoundly improved in MDA-MB-231 and BT549 controls, implying that FMNL2 elevation may be involved in ZOL or BMS3-induced suppressive role in breast cancer cell migration." (PMID 35379791, 2022). "We may infer that FMNL2 decreased the nuclear localization of p27 and the protein stability of p27, thus promoting CDK4/CyclinD1 kinase activity and cell proliferation of human breast cancer cells." (PMID 34193109, 2021). "However, the function of FMNL2 in breast cancer cell proliferation has not been reported." (PMID 34193109, 2021).
gastric cancer (4 papers, 2018 to 2023). A primary or metastatic malignant neoplasm involving the stomach. "Modulation on integrin internalization may be implicated in the role of FMNL2 in growth and migration of gastric cancer cells." (PMID 29881327, 2018). "We speculate that integrin internalization may be implicated in the role of FMNL2 in gastric cancer cells." (PMID 29881327, 2018). "Additionally, integrin internalization may be implicated in the role of FMNL2 in gastric cancer cells." (PMID 29881327, 2018). "Silencing the formin like 2 (FMNL2) gene has been shown to slow the growth of gastric cancer cells, demonstrating its therapeutic potential." (PMID 37762498, 2023). "FMNL2 knockdown suppresses growth of gastric cancer cells through suppressing internalization of integrins." (PMID 34193109, 2021). "Consistently, in our study, FMNL2 silencing declined integrin internalization induced by PKC in gastric cancer cells." (PMID 29881327, 2018). "As far as we know, our study is the first report showing direct evidence for the role of FMNL2 in gastric cancer growth." (PMID 29881327, 2018). "In our study, we also investigated the effect of FMNL2 silencing on migration and invasion of gastric cancer cells." (PMID 29881327, 2018). "Our study demonstrates for the first time that silencing FMNL2 suppresses proliferation, invasion and migration and induced apoptosis of gastric cancer cells." (PMID 29881327, 2018). "In this study, we also confirmed a similar effect of FMNL2 on the protein levels of EMT markers in gastric cancer cells." (PMID 29881327, 2018). "In the present study, we aimed to investigate the effect of FMNL2 silencing on gastric cancer cells." (PMID 29881327, 2018). "Our results showed that silencing FMNL2 suppressed proliferation, migration and invasion, and induced apoptosis of gastric cancer cells." (PMID 29881327, 2018). "We found that FMNL2 silencing suppressed migration and invasion of gastric cancer cells, indicating that FMNL2 also contributes to metastasis of gastric cancer cells." (PMID 29881327, 2018). "Effect of FMNL2 silencing on migration of gastric cancer cells was evaluated by wound healing assay." (PMID 29881327, 2018). "Our study reveals that silencing FMNL2 suppresses growth and metastasis of gastric cancer cells." (PMID 29881327, 2018). "FMNL2 silencing also suppressed migration and invasion of gastric cancer cells." (PMID 29881327, 2018). "In this study, we aimed to investigate the role of FMNL2 in gastric cancer cells." (PMID 29881327, 2018). "The results of our study indicate that FMNL2 may act as an oncogene in gastric cancer cells and has the potential to become a therapeutic target for gastric cancer." (PMID 29881327, 2018). "Silencing FMNL2 suppressed proliferation of gastric cancer cells and induced their apoptosis." (PMID 29881327, 2018). "In the present study, we explored the role of FMNL2 in gastric cancer cells." (PMID 29881327, 2018). "In our study, FMNL2 silencing suppressed proliferation of gastric cancer cells and induced their apoptosis, indicating that FMNL2 may contribute to gastric cancer growth." (PMID 29881327, 2018). "Our study indicates that FMNL2 may become a potential therapeutic target for gastric cancer." (PMID 29881327, 2018). "However, the role of FMNL2 in gastric cancer remains unclear." (PMID 29881327, 2018).
hepatocellular carcinoma (4 papers, 2021 to 2022). A malignant tumor that arises from hepatocytes. "Critically, our findings are validated by the fact that decreased FMNL2 expression has been regarded as a sign of poor outcome in hepatocellular carcinoma." (PMID 35379791, 2022). "Most reports are of cancers in which the expression of a given formin gene or protein is upregulated, although there are some exceptions, such as the DIAPH3 and FMNL2 proteins, in which the expression is downregulated in triple-negative breast cancer and hepatocellular carcinoma, respectively." (PMID 34685534, 2021). "The expression levels of formin-like 2 (FMNL2) are elevated in metastatic colorectal cancer cells 74 and decreased in hepatocellular carcinoma cells." (PMID 35154449, 2022).
colon cancer (3 papers, 2018 to 2025). "It was reported that circRNA_001569, as a sponge of miR-145, promoted proliferation and invasion of colon cancer through up-regulating FMNL2, which was a functional target of miR-145." (PMID 29881327, 2018). "For example, FMNL2 enhances the growth and metastasis of colon cancer in which FMNL2 is highly expressed." (PMID 29881327, 2018). "Consistently, the FMNL2 expression in colon cancer, which has a high FMNL2 level, is correlated with tumor invasion and lymphatic metastasis." (PMID 29881327, 2018). "Several microRNAs were reported to suppress growth of colon cancer through targeting FMNL2." (PMID 29881327, 2018). "FMNL2 is also found to boost invasion and migration of colon cancer." (PMID 29881327, 2018). "In colon cancer tissues, hsa_circ_001988 expression reduced and hsa_circ_001569 negatively correlated with miR-145 as a sponge by attenuating BAG4, E2F5, and FMNL2 expressions." (PMID 36313671, 2022).
glaucoma (3 papers, 2018 to 2025). Increased pressure in the eyeball due to obstruction of the outflow of aqueous humor. "The biological plausibility of FMNL2’s role in ocular structural disorders is further supported by its associations with primary open-angle glaucoma and related endophenotypes, including intraocular pressure (IOP) and vertical cup-to-disc ratio." (PMID 41320768, 2025). "Moreover, FMNL2 expression reduction, already known to be involved in glaucoma, causes huge Golgi dispersal, malformations of vesicular organelles and defective anterograde transport from the Golgi to plasma membrane." (PMID 32413970, 2020). "The current study identifies a total of nine novel loci associated with the risk of POAG or glaucoma at genome-wide significance that replicated in an independent sample, and demonstrates relevant function of FMNL2 and LMX1B using cell line and mouse experiments." (PMID 29891935, 2018). "Therefore, FMNL2 likely contributes to glaucoma susceptibility through its effect on elevated IOP." (PMID 29891935, 2018). "Functional studies support intraocular pressure-related influences of FMNL2 and LMX1B, with certain Lmx1b mutations causing high IOP and glaucoma resembling POAG in mice." (PMID 29891935, 2018). "Finally, functional characterization of FMNL2 and LMX1B points to a mechanistic effect on IOP levels, which supports their role as glaucoma risk genes." (PMID 29891935, 2018). "These included Angpt1, Ank, Cadm2, Fmnl2, Plce1, Thsd7a, and Tmtc2 at the novel POAG/glaucoma loci identified in the current study." (PMID 29891935, 2018).
cerebrovascular disease (2 papers, 2022 to 2023). "Surprisedly, a new study has shown that the FMNL2 gene participates in the development of cerebrovascular disease and AD, suggesting that changes in FMNL2 activity caused by cerebrovascular disease prevent effective clearance of toxic proteins from the brain, ultimately leading to AD." (PMID 40224594, 2023). "Interestingly, we found that increased FMNL2 expression (ENSG00000157827) was associated with brain infarcts and AD independently, suggesting that this gene may be involved in a shared molecular mechanism with cerebrovascular disease." (PMID 35608697, 2022).
COVID-19 (2 papers, 2023 to 2025). A disease caused by infection with severe acute respiratory syndrome coronavirus 2. "By 6 weeks post-inclusion (T2), COVID-19 hypermethylation of genes with lowest p-value included NXN, FMNL2, ZBTB46, SLC35F3, and SHQ1, and the hypomethylated genes included ELMO1, XBP1, GRIK1, TNFAIP8, and SH3BP5." (PMID 41227320, 2025).
esophageal cancer (2 papers, 2022 to 2024). A primary or metastatic malignant neoplasm involving the esophagus. "CircRNA TCFL5 promotes esophageal cancer cell proliferation, invasion, and migration by regulating the FMNL2/miR-543 axis, mediates macrophage M2 polarization, and promotes tumor growth in vivo." (PMID 38523627, 2024). "Furthermore, qPCR and western blot analysis showed that the expression of FMNL2 was dramatically increased in esophageal cancer tissues compared with normal tissues." (PMID 35646112, 2022). "In the present study, we demonstrated that overexpressing FMNL2 promoting miR-543 could partially reverse esophageal cancer development." (PMID 35646112, 2022). "In addition, FMNL2 was found upregulated in esophageal cancer by bioinformatic analysis of GSE6188, GSE13937, and GSE43732 microarrays, suggesting that FMNL2 might act as an oncogene in esophageal cancer." (PMID 35646112, 2022).
Intellectual disability (2 papers, 2011 to 2012). "A microdeletion on chromosome 2q region involving FMNL2 has previously been implicated in mental retardation, and association and linkage studies have implicated this same chromosomal region with susceptibility to autism (Imgsac." (PMID 22384361, 2011).
liver cancer (2 papers, 2022 to 2024). An epithelial or non-epithelial malignant neoplasm that arises from the liver. "It was found that FMNL2 was highly expressed in liver cancer and elevated expression level of FMNL2 was associated with worse overall survival (OS) of liver cancer patients." (PMID 36335129, 2022). "Consistently, it was also observed that FMNL2 was significantly up-regulated in liver cancer cell lines compared with normal liver cell line." (PMID 36335129, 2022). "We compared the expression levels of FMNL2 in liver cancer and normal samples and its prognostic significance using the RNA-seq and clinical data from TCGA database." (PMID 36335129, 2022). "These experimental results indicated that LINC00839 may promote liver cancer progression by up-regulating FMNL2 expression." (PMID 36335129, 2022). "Bioinformatic analysis showed that FMNL2 was up-regulated in liver cancer and correlated with patient unfavorable survival..Our data revealed FMNL2 may be a functional partner of LINC00839." (PMID 36335129, 2022). "Additionally, mechanistic investigations were performed to explore the potential mechanism of LINC00839 and its connection with FMNL2, which may provide a basis for clinical diagnosis and treatment of liver cancer." (PMID 36335129, 2022).
lung carcinoma (2 papers, 2016 to 2024). "In addition, ANGPTL4 can be secreted into exosomes by lung cancer cells and FMNL2 controls exosome secretion." (PMID 39479958, 2024). "Our data proved that RMRP acted as an oncogene LncRNA to promote the expression of KRAS, FMNL2 and SOX9 by inhibiting miR-206 expression in lung cancer." (PMID 27906963, 2016). "miR-206 was proved to act as a tumor suppressor miRNA in lung cancer through targeting the KRAS, FMNL2 and SOX9." (PMID 27906963, 2016).
metastatic cancers (2 papers, 2015 to 2019). A carcinoma which has spread from the original site of growth to another anatomic site. "FMNL2 is unique among formins in that it is upregulated in several metastatic cancers and is involved in the behavior and progression of cancer cells." (PMID 31751425, 2019). "Formin-like 2 (FMNL2—actin nucleation and assembly factor), upregulated in several metastatic cancers, interacts with RhoC to drive α2β1 and α5β1 integrin internalization/trafficking and invasive motility of cancer cells." (PMID 26635609, 2015).
oral squamous cell carcinoma (2 papers, 2020 to 2022). "FMNL2 regulates the invasiveness of cancer cells by driving β1-integrin internalization and RPL34 could promote cell growth and metastasis of oral squamous cell carcinoma." (PMID 32127786, 2020).
amyloid (1 paper, 2022). "A significant increase in FMNL2 expression was observed in the brains of patients with brain infarcts and AD pathology and was associated with amyloid and phosphorylated tau deposition." (PMID 35608697, 2022). "We used a transient knock-down of FMNL2 function in an acute amyloidosis zebrafish model, and a model of chronic amyloid pathology in mouse." (PMID 35608697, 2022). "To determine whether chronic amyloid pathology in mammalian models of AD would alter Fmnl2 expression and gliovascular remodeling, we utilized a well-established AD model APP/PS1dE9." (PMID 35608697, 2022).
atherosclerosis (1 paper, 2022). A disease characterized by the build-up of fatty material and calcium deposition in the arterial wall resulting in partial or complete occlusion of the arterial lumen. "We observed that in control brains, FMNL2 expression was punctate and scarce around the blood vessels, while in early onset AD and in AD with severe atherosclerosis, there was significant FMNL2 expression that delineated the blood vessels." (PMID 35608697, 2022).